CHI3L1 (chitinase 3 like 1)
Diseases named in the same sentence as CHI3L1 in open-access papers (continued):
Sharing a sentence is not in itself a finding about the gene and the disease.
tumor (continued). "Importantly, inflammatory and ECM related proteins characteristic of adipose tissue from obese subjects, such as osteopontin (OPN), chitinase-3 like-1 (YKL-40), tenascin C (TNC) and lipocalin-2 (LCN-2), have also been directly implicated in tumor growth." (PMID 27612200, 2016). "Also, the literature up to date lacks crucial documentation of CHI3L1 expression with respect to tumor grade and interface with survival." (PMID 27121858, 2016). "In addition, pathways that regulate tumor induction of Chi3l1 were defined and the effects of these pathways on tumor metastasis were evaluated." (PMID 27198666, 2016). "Furthermore, in breast and colon cancer it was shown that increased CHI3L1 levels correlate with tumor grade and poor differentiation of cancer cells." (PMID 26425658, 2015). "The role of CHI3L1 in tumor angiogenesis has also been noted." (PMID 26452028, 2015). "Thus, induction of expression of CHI3L1 in SCLC CTCs stems most likely from exposure of a fraction of the tumor cells to inflammatory cytokines produced by macrophages in the adjacent stroma tissue." (PMID 26425658, 2015). "The biological and physiological functions of CHI3L1 in cancer causing dissemination of tumor cells have not yet been elucidated." (PMID 26425658, 2015). "Using univariate analysis, high CHI3L1 expression (HR 3.03, 95% CI: 1.84 − 5.00, p < 0.001), advanced stage (HR: 5.20, 95% CI: 1.63 − 16.59, p = 0.005) and residual tumor size > 1 cm after debulking surgery (HR: 3.09, 95% CI: 1.81 − 5.26, p < 0.001) were risk factors for death." (PMID 26452028, 2015). "Therefore, once tumor formation was induced by carcinogen (AOM) injection, inherently increased CHI3L1 expression in MOLF mice allows drastically accelerated tumor growth than B6 mice with increased polypoid nodule numbers and sizes." (PMID 26440614, 2015). "Therefore, it is possible that enhanced bacterial/epithelial interaction due to increased CHI3L1 expression makes MOLF mice more susceptible to carcinogenesis and tumor cell expansion." (PMID 26440614, 2015). "A CHI3L1-neutralizing monoclonal antibody blocks tumor angiogenesis and progression." (PMID 26425658, 2015). "These higher levels of CHI3L1 could be due to expression by the pulmonary tissue itself and/or the tumor cells that have infiltrated by 5 weeks." (PMID 24399973, 2013). "Binding of chitin to CHI3L1 may neutralize the adverse effects of CHI3L1 on tumor growth and metastasis both by decreasing angiogenesis and increasing IFN-γ expression." (PMID 24399973, 2013). "Forty-eight primary tumours were scored for CHI3L1 protein expression." (PMID 18781180, 2008). "In fact, CHI3L1 may paradoxically promote tumor progression by stimulating the PD-1/PD-L1 axis." (PMID 40643503, 2025). "However, the elevated expression of chitinase 3-like 1 protein (CHI3L1), a secreted glycoprotein, in M2a macrophages promotes tumor cell invasion and metastasis by upregulating matrix metalloproteinases (MMPs) in various tumor cells." (PMID 40034694, 2025). "With tumours that show high-level CHI3L1/Chil1 expression, its inhibition may well counteract its tumorigenic properties and be therapeutic; however, duration of such treatment would need to be carefully evaluated to avoid loss of any protection CHI3L1/Chil1 affords." (PMID 40769579, 2025). "Moreover, based on the staining location on primary tumor sections, CHI3L1 and CHI3L3 were almost exclusively present at cellular necrosis sites, which were highly populated with Ly6G+ TANs, albeit with a much lower abundance in 66cl4 compared to 4T1 primary tumors." (PMID 38605414, 2024). "Moreover, as a general CLP blocker, chitin evokes enhanced anti-tumor immunity and concomitant tumor growth reduction compared to blockade of CHI3L1 alone, both treatments equally affecting lymphatic metastasis by hampering lymphatic vessel integration of macrophages." (PMID 38605414, 2024).
tumor (continued). "Since CHI3L1 plays a key role in the development of chronic inflammatory diseases and subsequent inflammation-mediated cellular carcinogenesis, therapeutic strategies that target CHI3L1 are a hotspot of current research and are expected to provide new avenues and approaches for tumor therapy." (PMID 39068486, 2024). "Therefore, CHI3L1 has been proposed as a prognostic biomarker for neoplastic diseases." (PMID 37887529, 2023). "Moreover, CHI3L1 is involved in the creation of an immuno-suppressive tumor microenvironment." (PMID 37958973, 2023). "Additionally, the mechanism through which CHI3L1 regulates neutrophil infiltration, which affects tumor progression and the drug response in BLCA patients, remains unclear." (PMID 37958973, 2023). "Furthermore, phosphorylated JNK and CHI3L1 expression also increased in tumor tissues." (PMID 37340009, 2023). "We assume that the anti‐Chi3L1 antibody may inhibit tumor growth by acting on macrophages." (PMID 34861103, 2022). "We investigated whether anti‐Chi3L1 antibodies altered macrophage polarization in tumor tissue." (PMID 34861103, 2022). "Besides, baseline tumour in the response group showed a moderately higher CHI3L1 IHC score." (PMID 36581917, 2022). "Chitinase-3 like-protein-1 (CHI3L1), a chitinase-like protein, is generated and released by various cells, including macrophages, microglia, including macrophages, microglia, neutrophils, synoviocytes, chondrocytes, fibroblast-like cells, smooth muscle cells, and tumor cells." (PMID 36685530, 2022). "Consequently, our study suggests that the anti‐Chi3L1 antibody may regulate the tumor microenvironment in metastatic sites by affecting macrophage biology." (PMID 34861103, 2022). "Therefore, the anti‐Chi3L1 antibody could inhibit tumor migration through M2 polarization suppression." (PMID 34861103, 2022). "Therefore, we hypothesize that CHI3L1 release is mainly responsible for astrocytic promotion of tumor malignancy." (PMID 31561550, 2019). "Since Chi3l1 deficiency reduced IL-4 production in Th2 cells while increasing IFNγ expression in Th1 and CD8 T cells, targeting Chi3l1 could provide prominent anti-tumor effect by driving Th1 response while suppressing the activity of tumor-promoting Th2 cells." (PMID 29403003, 2018). "Therefore, we hypothesized that specific immune regulatory function of Chi3l1 that drive Th2 polarization while inhibiting Th1 activation may contribute to the tumor development and progression." (PMID 29403003, 2018). "Therefore, immune, inflammatory or stromal cells in the tumor microenvironment may also affect the biological behavior of tumor cells by secreting CHI3L1." (PMID 30165890, 2018). "Expression of CHI3L1 in the inflamed pulmonary environment may affect the function of local lung macrophages, and thereby favor the production of pro-angiogenic substances that promote tumor establishment and growth." (PMID 24399973, 2013). "CHI3L1 was moderately expressed in the cytoplasm of LUAD cells, but barely in tumor stroma of primary LC tissue." (PMID 41362730, 2026). "Immumohistochemical (IHC) staining verified that CHI3L1 was strongly expressed in the cytoplasm of LUAD cells and diffusely secreted into tumor stroma of LC-BoM tissue." (PMID 41362730, 2026). "Disrupting astrocyte–tumor cell interactions, targeting key signaling pathways such as STAT3, CHI3L1, and PPAR-gamma, and developing microRNA-based therapies are promising strategies for inhibiting astrocyte-mediated tumor progression." (PMID 39858080, 2025). "In this context, CHI3L1 acts as a downstream effector of STAT3 and promotes tumor progression by enhancing the production of inflammatory cytokines." (PMID 40643503, 2025). "In agreement with the protein expression data, mRNA levels of the the genes CHI3L1 and SPP1 were also higher in tumor samples than in controls." (PMID 40703808, 2025).
tumor (continued). "The AUC value of the model consisting of the four genes (CHI3L1, FCGBP, VSIG2, and TFF2) outperformed other tumor markers and performed well in predicting the prognosis of GC patients." (PMID 40084401, 2025). "Immunohistochemical staining of nude mouse subcutaneous tumor model of SOX2, CD44, CHI3L1, and CD24 in vivo shows the same result, and IHC staining of TAM markers CD68 had no obvious change." (PMID 39619148, 2024). "More specifically, CHI3L1 drives immunosuppressive TAMs in the TME, but also contributes to the inhibition of anti-tumor (type 1) T-cell responses and natural killer (NK) cell activity." (PMID 38605414, 2024). "Chitin + anti-PD-1 combination treatment had an add-on effect in the 4T1-based model with a more significant reduction of CHI3L1 and CHI3L3 serum levels compared to untreated and anti-PD-1-treated tumor-bearing mice." (PMID 38605414, 2024). "In recent studies, researchers have discovered that a direct chemotactic stimulant, the tumor-produced cytokine Chitinase-3-like 1 (Chi3l1, YKL-40/CHI3L1 in humans), promotes NET formation in TNBC." (PMID 39107856, 2024). "CHI3L1 suppresses the antitumor response of NK cells and potentially other effector cells (e.g., CD8 + T cells), allowing tumor cells to escape recognition and attack by the immune system and maintaining inflammatory cell recruitment." (PMID 39068486, 2024). "CHI3L1 can bind to TMEM219 and promote tumor growth and invasion by activating Erk1/2 and Akt signaling." (PMID 38177294, 2024). "Inhibiting CHI3L1(YKL40) production through RNAi has shown potential in impeding cancer cell proliferation and inducing cell death, leading to a decreased tumor size." (PMID 38543093, 2024). "The cited 2023 pioneer study additionally showed that CHI3L1 serves as a TAN chemoattractant, which in turn reduces TAN(-precursor) infiltration in the primary tumor and promotes T-cell exclusion in the TME through formation of NETs." (PMID 38605414, 2024). "Li found that Chi3l1 inhibited miR-590-3p expression through the PI3K/Akt pathway, thereby promoting tumor angiogenesis." (PMID 38291404, 2024). "Their anti-CHI3L1 antibody (so-called FRG), PD-1 antibody, and CTLA-4 antibodies exhibited substantial anti-tumor effects and displayed additive responses in metastasis models." (PMID 38667293, 2024). "Previous studies have shown that semaphorin 7a (SEMA7A), as upstream regulator of CHI3L1, stimulates macrophage/TAM integration into lymphatic vessels to facilitate lymphatic entry and spreading of tumor cells." (PMID 38605414, 2024). "Cancer cells, particularly cancer stem cells, produce chitinase-3-like protein 1 (CHI3L1), fostering neutrophil recruitment and exerting a pro-tumor function by modulating immunosuppressive T cell functions." (PMID 38474175, 2024). "CHI3L1 interacts with CD44 and IL-13Ra2, activating pathways such as AKT and ERK1/2, which in turn promote tumor growth and invasion." (PMID 38177294, 2024). "Immunohistochemistry (IHC) staining performed on non-tumor brain tissue and GBM sections demonstrated a higher concentration of CHI3L1 in GBM." (PMID 39000203, 2024). "The glycoprotein YKL-40 (CHI3L1) is a potential biomarker involved in inflammation and tumor processes." (PMID 38003487, 2023). "To investigate the potential role of CHI3L1 in BLCA, we initially analyzed its expression in various cancer types by using data from the Tumor Immune Estimation Resource (TIMER)." (PMID 37958973, 2023). "Patients with tumor cells with low EMP3 and CHI3L1 expression levels had a better prognosis than patients with tumor cells with high EMP3 and CHI3L1 expression levels." (PMID 37887529, 2023). "CAFs regulate tumor growth, metastasis, and angiogenesis by the secretion of transforming growth factor-β (TGF-β), IL-6, CXCL12, and chitinase-3-like-1 (CHI3L1)." (PMID 37108109, 2023).
tumor (continued). "By performing immunohistochemistry of PDO155 and pathology specimens of this patient, we confirmed that CST3 and CHI3L1 proteins were heterogeneously expressed in PDO155 and even in the original tumor tissue." (PMID 36810117, 2023). "CHI3L1 also induces the expression of pro-tumorigenic molecules, including CXCL2, MMP-2, and MMP-9, which contribute to tumor growth and proliferation." (PMID 37480002, 2023). "WFDC2 can be measured as a tumor marker in Japan, and thus, GDF15 was excluded and WFDC2, CHI3L1, and KRT19 were used as the variables of classification." (PMID 36331721, 2023). "Another inflammatory marker gaining attention as a potential biomarker of early-stage CRC is chitinase-3-like protein 1 (CHI3L1), a glycoprotein produced by cells including macrophages, neutrophils and tumour cells." (PMID 35203465, 2022). "Therefore, F-actin may contribute to extracellular secretion of CHI3L1 in GBM tumor cells." (PMID 36276655, 2022). "We found that the anti‐Chi3L1 antibody inhibited MMP9 and cyclin D1 expression compared with the vehicle‐treated tumor tissues." (PMID 34861103, 2022). "Macrophages are known to promote tumor cell migration through the secretion of proteins, such as EGF, CHI3L1, IGF1, FN1, TNC and TGFBI." (PMID 36551640, 2022). "All together, these studies demonstrate that bispecific antibodies that target CHI3L1 and CTLA-4 have impressive antitumor effects while inducing CD8+ cytotoxic T cell differentiation and tumor cytotoxicity." (PMID 36618349, 2022). "While CD4+ memory resting T cells contribute most T-cells within the tumour microenvironment (TME), their presence is highly influenced by CCL2, ANG, CHI3L1, IL-6 and IL-8." (PMID 36430641, 2022). "Anti‐Chi3L1 antibody treatment reduces M2 polarization with STAT6‐dependent PLG signaling, eventually reducing tumor growth and cancer metastasis." (PMID 34861103, 2022). "Frozen tumor and normal sections were co-immunostained for CHI3L1 and CD206 to determine the correlation between CHI3L1 distribution and M2 macrophage infiltration." (PMID 36276655, 2022). "We have identified some of the molecular characteristics of the high-motility mesenchymal-like phenotype in our patient-derived cell model, most notably high gene expression levels of FN1, CHI3L1, and SERPINE1 in relation to other tumor-derived reactive glia." (PMID 35803925, 2022). "These immunosuppressive TME and aggressive tumor phenotype are blocked by CHI3L1 nAbs through shifting M2 to anti-tumor M1, decreasing Tregs/CD8+ T ratio and attenuating oncogenic cancer signaling to reduce tumor growth and metastases." (PMID 34987649, 2022). "Chitinase 3-like 1 (CHI3L1, YKL40/BRP39) has been reported to accelerate the recruitment of macrophages into tumor tissues and to promote tumor angiogenesis in colorectal patients." (PMID 33959512, 2021). "CHI3L1 up-regulates pro-inflammatory mediators, CCL2, CXCL2 and MMP-9, all of which contribute to tumor growth and metastasis, and treatment with chitin can significantly reduce these effects." (PMID 33937022, 2021). "The CHI3L1, MMP2, and IL8 form a triad based on the correlation matrix, which seems to play a central role in tumor local and distal development." (PMID 33846436, 2021). "Tumor expression of TGFBI, IGFBP3, and CHI3L1 were positively correlated with PDGFD and PDGFRB expression in TCGA LGG dataset, respectively." (PMID 34539622, 2021). "The tumor volumes and weights of B16F10 lung melanoma transduced by Chi3L1 shRNA were significantly smaller than in those of the control shRNA mice." (PMID 32127023, 2020). "Combined antiangiogenic therapies targeted against CHI3L1 and VEGF can significantly reduce tumour angiogenesis and consequently inhibit tumour growth." (PMID 30834271, 2019). "We identified an increased expression of genes that were previously found in the astrocytes from tumor specimens, (HLA-DRA, CHI3L1 SERPINA1, CCL18, CD37, and CD274)." (PMID 31186414, 2019).
tumor (continued). "CHI3L1 and LCN2 levels were subsequently measured in primary tumor lysates and sera from 4T1 + RAW264.7 and 4T1 inoculated mice and showed a progressive increase from 3 to 5 w p.i.." (PMID 30111338, 2018). "The genetic and chemical ablation of Chi3l1 in T cells significantly enhances Th1 and CTL responses and inhibits tumor growth and lung metastasis." (PMID 29403003, 2018). "In this work we observed an overexpression of three specific glycosylation‐related genes, CHI3L1, KLRC3 and PRUNE2 in CSC from cancer cell lines and human primary tumour cells." (PMID 27641066, 2017). "We characterized the mechanisms that Chi3l1 uses to foster tumor progression and the ability of the RIG-like helicase (RLH) innate immune response to control Chi3l1 elaboration and pulmonary metastasis." (PMID 27198666, 2016). "SCLC is characterized by high numbers of circulating tumor cells (CTCs) and we were able to expand several CTC lines ex vivo and to relate chitinase-3-like-1/YKL-40 (CHI3L1) as marker." (PMID 26328272, 2015). "Our study indicated that a high CHI3L1 expression was an independent prognostic factor for EOC, even in the patients whose residual tumor size < 1cm after debulking surgery or who receiving paclitaxel-platinum chemotherapy." (PMID 26452028, 2015). "For example, heparin decorations on Syndecan 1 (Syn1) are necessary for Chi3L1-mediated Syn1 interaction with the integrin αvβ3, which leads to FAK signaling and ERK1/2 activation, which promotes tumor angiogenesis." (PMID 25595947, 2015). "ELISA measurements demonstrated that significantly higher levels of CHI3L1 were also present in both BALF samples and total lung homogenates at 5 weeks post-tumor cell implantation, compared to the 2-week time point." (PMID 24399973, 2013). "Additionally, they secrete arginase II (Arg2), chitinase-3-like protein 1 (CHI3L1/YKL-40), and the anti-inflammatory cytokines IL-10 and TGF-β, which contribute to their immunosuppressive and tumor-promoting roles." (PMID 40771826, 2025). "CHI3L1 interacts with multiple receptors, such as RAGE, IL-13Rα2, and syndecan-1/αVβ3, triggering pathways involved in inflammasome activation, neuronal inflammation, tumor progression, angiogenesis, apoptosis, and amyloid-beta (Aβ) accumulation." (PMID 39827337, 2025). "Additionally, CHI3L1 from the CAF aligns the surrounding stroma to facilitate cancer cell intravasation and promote early tumor metastasis." (PMID 40766310, 2025). "CHI3L1 has also been reported to promote inflammatory cytokine production through its interaction with RAGE, thereby contributing to chronic inflammation and the development of the tumor microenvironment." (PMID 40643503, 2025). "Furthermore, CHI3L1 induces the secretion of CXCL8 and IL-6, which are proinflammatory cytokines that can also play a role in tumor progression and invasion." (PMID 38177294, 2024). "CHI3L1(YKL40) can regulate immune checkpoint gene expression such as PD-L1, PD-L2, PD-1, LAG3, and TIM3, which may enhance immune suppression in the tumor microenvironment, thus resulting in cancer progression and lymphatic spread." (PMID 38543093, 2024). "Recently, a growing body of research has indicated that chitinase-3-like protein 1 (CHI3L1; also known as breast regression protein 39 [BRP-39] in mice) may serve as an important marker of chronic inflammation and subsequently promote tumor progression." (PMID 39068486, 2024). "CHI3L1 can activate TGF-β signaling by binding to its receptor, thus leading to the production of proinflammatory cytokines and the recruitment of immune cells, which can promote tumor growth and metastasis." (PMID 38177294, 2024). "Moreover, the secretion of CHI3L1 by macrophages, CD4+ T cells, and CD8+ T cells fosters an immunosuppressive tumor microenvironment." (PMID 37958973, 2023). "CHI3L1, COL1A1, and CXCL14 have been shown to be related to tumor metastasis and invasion." (PMID 37480002, 2023).